HIF1A (hypoxia inducible factor 1 subunit alpha)
Diseases named in the same sentence as HIF1A in open-access papers (continued):
Sharing a sentence is not in itself a finding about the gene and the disease.
gastric cancer (continued). "Studies have shown that wogonin can negatively regulate HIF-1α and expression of monocarboxylate transporter-4 (MCT-4) to inhibit energy metabolism, cell proliferation, and angiogenesis in human gastric cancer cells (SGC-7901) and human lung adenocarcinoma cells (A549)." (PMID 36661523, 2023). "In addition, the positive feedback of HIF-1α/miR-301a-3p/PHD3 contributes to promoting the proliferation, invasion, migration, and EMT of gastric cancer cells." (PMID 35847022, 2022). "For example, lncRNA-PMAN was upregulated by HIF-1α and enhanced the stability of SLC7A11 mRNA, which suppressed the accumulation of reactive oxygen species (ROS) and irons in gastric cancer cells, and thus protected gastric cancer cells from ferroptosis induced by Erastin and RSL3." (PMID 36612069, 2022). "Terpenoids: Oleanolic acid (OA) inhibited tumor growth in human gastric cancer cells (MKN-45 and SGC-7901) by decreasing HK2 and PFK1 expression and intracellular activity, as well as decreasing HIF-1α expression and nuclear abundance, hence reduced glycolysis and induced cell apoptosis." (PMID 36339566, 2022). "RA simultaneously inhibits the expressions of HIF-1α, IL-6, and signal transducers and activators of transcription 3 (STAT3), along with the phosphorylation of STAT3, suggestive of glycolytic inhibition in gastric cancer cells through the IL-6/STAT3 pathway." (PMID 36438836, 2022). "Similarly, for gastric cancer, cucurbitacin B reversed the multi-drug resistance of the SGC7901/DDP gastric cancer cells by downregulating the drug-resistant protein HIF-1a and P-pg." (PMID 36585670, 2022). "Likewise, in the pathogenesis of gastric cancer, the circMAT2B/miR-515-5p/HIF-1α feedback circuit reinforces HIF-1α signaling, which then amplifies the oncogenic effect of circMAT2B, eventually facilitating glycolysis." (PMID 35842651, 2022). "GRg3 inhibits the expression of HIF-1α and VEGF in the human gastric cancer cells line BGC823 and may affect the peritoneal implantation of gastric cancer metastasis by suppressing their expression." (PMID 36313365, 2022). "Furthermore, the rescue experiments disclosed that HIF-1α and β-catenin pathways overexpression reduced the effects of AKIP1 knockdown on invasion, CD133+ cell proportion, and sphere number/1,000 cells in gastric cancer cells under hypoxia." (PMID 35355804, 2021). "EGCG also significantly suppressed the accumulation of HIF1α protein in gastric cancer cells but did not affect the expression of HIF-1α mRNA." (PMID 33918290, 2021). "The HIF-1α-dependent radioprotection of hypoxic gastric cancer cells appears to be realized via the HIF-1α-mediated expression of human epididymis protein 4 (HE4), whose upregulation is responsible for the high resistance of gastric cancer to radiotherapy." (PMID 33806538, 2021). "It has been reported that in human gastric cancer cell model, DHTS could inhibit HIF-1α expression by suppressing its protein accumulation." (PMID 34400891, 2021). "Taken together, miR-4646-5p/PHD3/HIF1A axis upregulates RhoA transcription and the RhoA activation can be triggered by miR-4646-5p/ABHD16A-mediated lipid metabolite lyso-PS accumulation in gastric cancer cells." (PMID 33875796, 2021). "Researchers found that Scutellaria baicalensis Georgi can regulate the expression of TLR8, HIF-1α, PDGFβ, and PTEN in gastric cancer cells, which can inhibit invasion, migration, and epithelial-mesenchymal transition of gastric cancer cells through NF-κB/Snail signaling pathway." (PMID 34421596, 2021). "Moreover, in gastric cancer, CTHRC1 was reported to promote tumor metastasis through the HIF-1α/CXCR4 signaling pathway." (PMID 34968391, 2021). "This study confirmed that NPRA could bind to HIF-1α and maintain the stability of HIF-1α, which provided a basis for NPRA to promote angiogenesis of gastric cancer." (PMID 34671022, 2021).
gastric cancer (continued). "Among them, an epigenetic regulator TET1 and HIF‐1A were evidently regulated, which could bridge epigenetic mechanism with NUTM2A‐AS1/miR‐376a‐regulated gastric cancer." (PMID 33089970, 2020). "Moreover, an interesting interaction between the two HIF-1α regulating lncRNAs DANCR and LET was reported in gastric cancer." (PMID 32640630, 2020). "In gastric cancer cells, lncRNA zinc finger E-box-binding homeobox 2 antisense RNA 1 (ZEB2-AS1) was overexpressed and inhibited miR-143-5p expression by acting as a miRNA sponge, which increased ROS levels and HIF-1α expression to promote cancer progression." (PMID 35006436, 2020). "To confirm the role of HIF-1α in mediating the suppressive effect of compound 9 on tumor cell-induced angiogenesis, we investigated the effect of compound 9 on HIF-1α expression in AGS gastric cancer cells." (PMID 32751120, 2020). "Similar to the classical interactive mode between HIF-1α and miRNAs, HIF-1α can also directly interact with the HREs in the lncRNA BC005927 promoter region, inducing lncRNA BC005927 to play its oncogenic role in gastric cancer by upregulating EPH receptor B4 (EPHB4)." (PMID 32014012, 2020). "Furthermore, crocin inhibited the migration and invasion of AGS and HGC-27 gastric cancer cells by a reduced level of Krüppel-like factor 5 (KLF5), HIF-1α, and EMT activity by increasing E-cadherin and decreasing Snail and N-cadherin." (PMID 33321708, 2020). "In gastric cancer tissues, the difference in the expression between HIF-1α and NDRG2 was not statistically significant, (Fisher, P=1.000)." (PMID 33817155, 2019). "This study aims to investigate the differences in the expression of hypoxia-inducible factor-1α (HIF-1α), N-myc downstream-regulated gene 2 (NDRG2) and epithelial mesenchymal transition (EMT)-related proteins in normal gastric tissues, gastric cancer tissues and lymph node metastasis." (PMID 33817155, 2019). "GATA3 was demonstrated to interact with HIF-1α to enhance cancer cell invasiveness, and inhibition of HHIP promoter methylation suppressed human gastric cancer cell proliferation and migration, which would affect the treatment and prognosis of patients with gastric cancer." (PMID 31281358, 2019). "Knockdown of PVT1 could reverse cisplatin-resistance in the resistant gastric cancer cells by regulating the expression of MDR1, MRP, mTOR and HIF-1α." (PMID 29108264, 2017). "In our study, we found that HIF-1α-induced miR-421 significantly attenuated the apoptotic ability induced by cisplatin, and reversed the cisplatin induced activation of caspase-3 and cleavage of PARP in gastric cancer cell lines." (PMID 27016414, 2016). "Moreover, we treated gastric cancer cell line SGC-7901 xenografted male BALB/c-nude mice (4 weeks old) with BAY 87-2243, a HIF-1α specific inhibitor, for 15 days." (PMID 27016414, 2016). "To investigate the potential interaction between HIF-1α, ANXA1 and MYC in primary gastric cancer, we performed a bioinformatics analysis of co-occurrence and mutual exclusivity using a RNA-seq data-set from the TCGA data-base with 265 samples of stomach adenocarcinoma (cBioPortal)." (PMID 26760764, 2016). "Unlike in ovarian and gastric cancer, induction of HIF1-α occurs through integrin αvβ3 binding and activation of NF-κB." (PMID 27023622, 2016). "Moreover, BECN1 expression was negatively correlated with expression of HIF-1α (P = 0.042) and GLUT-1 (P = 0.046), and positively correlated with E-cadherin expression (P = 0.006) in gastric cancer tissues." (PMID 26497999, 2015). "Hypoxia (1% O2, 8 h) was shown to induce HIF-1α and HIF-2α expression in gastric cancer cell lines." (PMID 25590810, 2015). "We discovered that inhibition of autophagy in gastric cancer cells reduced the production of citrate and fumarate, promoted the expression and membrane translocation of GLUT-1 as a result of the increased HIF-1α expression, consequently enhanced the glucose uptake and lactate production." (PMID 26497999, 2015).
gastric cancer (continued). "What's more, immunohistochemical and PET analysis showed that NAC could suppress autophagy defect induced up-regulation of HIF-1α and GLUT-1, as well as glucose uptake in gastric cancer xenografts, which is further sustaining our hypothesis." (PMID 26497999, 2015). "Therefore, analyses combining previous results may show a possible axis of action by HIF-1α and its oncogenic signaling pathway, which could contribute to improvements in prognosis assessment, functional analysis, and drug-targeted therapy in the prevention and treatment of gastric cancer." (PMID 24647137, 2014). "Gastric cancer specimens were confirmed to express both CD133 and HIF-1α." (PMID 23558457, 2014). "Their results showed that HIF-1α and HIF-2α were more highly expressed in metastatic gastric cancers compared to non-metastatic carcinomas, indicating that HIF-1α is likely a major determinant of invasion and metastasis in several tumor types." (PMID 24614305, 2014). "In order to investigate the correlation between the expression of hypoxia-inducible proteins and the stem cell-related proteins Oct4 and Nestin, we measured HIF-1α, HIF-2α, Oct4, and Nestin expression in 175 gastric cancer tissue samples by immunohistochemical staining." (PMID 25142304, 2014). "Hence, our study shows for the first time that HIF-1α overexpression is correlated to not only OS, but also DFS, in gastric cancer patients." (PMID 24614305, 2014). "Our findings indicate that HIF-1α/PTEN/CD44v6/Survivin, as measured by immunohistochemistry, can be used to predict the prognosis and potential for invasion and metastasis in Asian patients with gastric cancer." (PMID 24647137, 2014). "Hence, the objective of the present study was to analyze the prognostic values of HIF-1α, TGF-β, VEGF and pERK1/2 in gastric cancer patients following gastrectomy." (PMID 24614305, 2014). "Next, the expressions of HIF-1α and Foxp3 in tumor tissues were compared in patients with nonmetastatic (n = 52) and metastatic (n = 47) gastric cancer." (PMID 23723999, 2013). "The results from our immunohistochemical analysis of human gastric cancer tissues demonstrated that the expression of PDK-1, a gate-keeping enzyme that regulates carbohydrate transport into the mitochondria, was significantly correlated with HIF-1α expression." (PMID 23135628, 2013). "Immunohistochemistry was used to detect the expression of DEC1, hypoxia-inducible factor 1(HIF-1α) and Ki67 in 173 human gastric cancer samples and adjacent non-tumor tissues samples." (PMID 23445622, 2013). "In this study, we used immunohistochemistry to evaluate the expression status and clinicopathological features of DEC1 and HIF-1α in 173 human gastric cancer samples and its adjacent non-tumor tissues by immunohistochemistry." (PMID 23445622, 2013). "Likewise, HIF-1α and HIF-2α were highly expressed in metastatic gastric cancers and correlated significantly with clinical stage." (PMID 22454562, 2012). "The precise mechanism(s) of the reduced invasive capacity of AGS and MKN28 gastric cancer cells without functional HIF-1α has not been determined here and remains a topic for future research." (PMID 19223895, 2009). "Our results show that in both gastric cancer cell lines investigated, HIF-1α protein is not detectable under normoxic conditions by means of western blot." (PMID 19223895, 2009). "Immunhistochemistry for HIF-1α showed specific staining at the invading tumour edge in 90% of human gastric cancer samples, whereas normal gastric tissue was negative and only a minority of early gastric cancers (T1 tumours) showed specific staining." (PMID 19223895, 2009). "Furthermore, SHMT2 regulates HIF1α expression through both enzymatic and non-enzymatic functions in gastric cancer." (PMID 40097394, 2025).
gastric cancer (continued). "We observed an increase in MALAT1 expression in gastric cancer tissues compared to normal tissues as well as a moderate positive correlation between CD163 (an indicator of TAM infiltration in tumors) and HIF‐1α gene expression (but not δ‐catenin) in gastric cancer tissues by analyzing TCGA data." (PMID 38639382, 2024). "Therefore, whether HIF-1α acts as a mediator of the upregulation in P-gp, MRP, or anti-apoptotic proteins in MKN45 gastric cancer cells exposed to paclitaxel needs validation with knockdown/out experiments." (PMID 36846589, 2023). "Moreover, HDAC inhibitors and proteasome inhibitors have been evaluated in several clinical trials for treating gastric cancer without emphasizing HIF-1α inhibitory action." (PMID 36846589, 2023). "Similarly, gastric cancer 58As9 cells exposed to 1% oxygen for 12, 24, and 48 h showed an increase in MMP-1 expression, which decreases in HIF-1α knockdown cells and with the use of the HIF-1α inhibitor YC-1." (PMID 38069210, 2023). "Therefore, both V-ATPase and HIF-1α provide effective therapeutic targets, and reducing the expression of V-ATPase and HIF-1α can increase the effectiveness of chemotherapeutic drugs and even reverse the drug resistance of gastric cancer cells." (PMID 36187789, 2022). "In addition, we demonstrated that HIF-1α can specifically activate transcription of an S100A4 promoter through the HIF-1α binding site, probably located at − 1838 to − 1829; this is in contrast to earlier study that used a gastric carcinoma cell line." (PMID 35392912, 2022). "Mechanistically, IL-32 has been demonstrated to promote changes in gastric cancer cell morphology, facilitating their migration, and to enhance their potential for invasiveness by upregulating the expression of matrix metalloproteinases (MMP)-2 and 9, VEGF-A, and IL-8 via HIF-1α activation." (PMID 33020452, 2020). "In particular, HIF-1α is directly responsible for the epithelial to mesenchymal transition (EMT)-like changes of hypoxia-induced gastric cancer stem cells, which may result in the recurrence and metastasis of gastric cancer." (PMID 29997345, 2018). "Incubation of EBV-positive gastric carcinoma AGS-Akata and SNU-719 and Burkitt lymphoma Sal and KemIII cell lines with a prolyl hydroxylase inhibitor, L-mimosine or deferoxamine, or the NEDDylation inhibitor MLN4924 promoted rapid and sustained accumulation of both HIF-1α and lytic EBV antigens." (PMID 28617871, 2017). "In our study, we found that transfection of HIF-1α-induced-miR-421 significantly down regulated the epithelial biomarker E-cadherin and up regulated N-cadherin, Fibronectin, Vimentin, Snail, Slug, Twist, MMP-2, and MMP-9 in cisplatin treated gastric cancer cell lines." (PMID 27016414, 2016). "However, the potential mechanisms of HIF-1α and miR-421 in gastric cancer have not been well elucidated." (PMID 27016414, 2016). "Interestingly, 80.4% of HIF-1α-positive gastric cancers were negative for ANXA1, further supporting the notion of mutual exclusivity." (PMID 26760764, 2016). "When we treated gastric cancer xenografted nude mice with a HIF-1α-specific inhibitor, echinomycin, for 10 days, echinomycin decreased the expression of miR-382 by 0.2-fold in tumor tissues, confirmed by real-time PCR, indicating that HIF-1α is involved in miR-382 expression in tumor tissues." (PMID 24914051, 2014). "Along with the results from gastric cancer patients tissue samples, we concluded that, HIF-1α and HIF-2α may both important regulator of GCCs behavior under hypoxia, HIF-1α seemed to be a predominant hypoxia regulator in milky spots hypoxic microenvironment during GCPD." (PMID 25142304, 2014). "In addition, the author revealed that the hypoxia-induced HIF-1α expression increases the expression of anti-apoptotic factor Bcl-2 and the multidrug resistant gene MRP1, suggesting a novel mechanism of hypoxia-induced chemoresistance in gastric cancer." (PMID 24216696, 2013).
gastric cancer (continued). "Interestingly, a recent study from Japan demonstrated lower efficacy of 5-FU-based chemotherapy in HIF-1α-expressing human gastric adenocarcinomas, strengthening the perception of HIF-1 as a pivotal factor in the determination of gastric cancer chemoresistance." (PMID 20706634, 2010). "However, the interaction between HIF-1α and B7H3 in gastric cancer remains unclear." (PMID 41710663, 2026). "In gastric cancer (GC), activation of JAK2/STAT3 could promote HIF-1α/VEGFA axis, and bolsters macrophage polarization, thus facilitating GC metastasis and angiogenesis." (PMID 39130627, 2024). "SMAD7, HIF-1α gene and HIF-1α protein may be jointly involved in tumor development and prognosis (act as oncogenic factors), while SEC13, GHRL, and lncRNA GHRLOS may act as tumor suppressor factors and thus could be considered as novel therapeutic targets for gastric cancer." (PMID 35449150, 2022). "Taken together, the results suggest that HIF-1α inhibition plus GI may be an ideal therapy, because the apoptosis due to the destruction of ROS homeostasis is specifically induced in gastric cancer that grows under a hypoxic environment, but not in the normal tissue under the aerobic conditions." (PMID 26339797, 2015). "In addition, the upregulation of Survivin by HIF-1α and PTEN contributed to cisplatin (CDDP) resistance, indicating that inhibition of these pathways may be a potential strategy for overcoming CDDP resistance in the treatment of gastric cancer." (PMID 24647137, 2014). "At present, the correlation between the expression of HIF-1α and NDRG2 in gastric cancer and lymph node metastasis tissues has not been reported." (PMID 33817155, 2019). "Previously, we established a functional link between HIF-1α-controlled reduction of ROS and anchorage independence of gastric cancer cells, implicating HIF-1α in the pathogenesis of gastric cancer in the absence of hypoxia." (PMID 20706634, 2010). "Plk1 was independent of HIF-1α and HIF-2α in stomach cancer, uterine cancer, and uveal melanoma." (PMID 33547392, 2021). "For example, patients with HIF-1α-negative/focally positive and HIF-2α-negative gastric cancers had an average disease-free survival of 81 (95% CI 59−103) months compared with 25 (95% CI 11−39) months for those with invasive edge HIF-1α- and HIF-2α-positive tumours." (PMID 18283323, 2008). "Since the lack of VHL, which results in the stabilization of HIF-1α, is related to the overexpression of KLF8 in renal cell carcinoma, the research group investigated whether KLF8 is involved in hypoxia-induced chemoresistance in gastric cancer." (PMID 36846589, 2023).